CD4 (CD4 molecule)
Diseases named in the same sentence as CD4 in open-access papers (continued):
Sharing a sentence is not in itself a finding about the gene and the disease.
colitis (continued). "An acute colitis model was induced with either dextran sulfate sodium (DSS) or trinitrobenzenesulfonic acid (TNBS) and a chronic colitis model was induced by CD4+CD45RBhi T cell transfer from either wild-type C57BL/6 or Il17a−/− mice." (PMID 31941937, 2020). "In this experiment, ZFP36L2 iTregs or mock iTregs were adoptively co-injected with naive CD4+ T cells into RAG2−/− mice, and the development of colitis was evaluated by histological analyses and by its effect on the mice weight." (PMID 32655569, 2020). "The number of CD45RA−CD62L−CCR7− Tem cells and CD4+ Tem cells increased significantly, while the number of CD8+ Tem cells decreased significantly in DSS-induced colitis." (PMID 32714185, 2020). "Alpinetin, a flavonoid, was found to suppress colitis through upregulation of miR-302 and decreasing the expression of DNMT-1, and thereby the methylation of FoxP3 promoter in CD4+ T cells in mice, leading to the induction of Tregs." (PMID 33105907, 2020). "Rg3-RGE + PT also up-regulated mice’s CD4+ cells, and the Th2 cytokine, IL-4, was identified as the target to protect mice from DSS-induced colitis." (PMID 33182623, 2020). "The results showed that the expression of GITR on the surface of regulatory and effector CD4+T cells was dispensable for progression of the disease, but the presence of GITR on DCs and macrophages was requisite for controlling colitis." (PMID 33163004, 2020). "In contrast with mice in the DSS group, the numbers of CD4+CXCR5+ BCL-6+, CD4+CXCR5+ICOS+, and CD4+CXCR5+PD-1+ T cells were decreased, and CD4+CXCR5+Blimp-1+ T cells were significantly increased after colitis was treated with SSP and 5-ASA for 7 days." (PMID 32581849, 2020). "The frequency of Th17 cells in the MLNs of experimental colitis mice decreased after injection of QCHS-treated DCs, whereas the frequency of CD4+CD25+Foxp3+ Tregs was upregulated." (PMID 32967687, 2020). "It is noteworthy that CD4+CD25+ Treg has been shown to prevent and resolve murine colitis, and the cure of murine colitis by these cells was dependent on the presence of IL-10." (PMID 31888063, 2019). "In this colitis model, a large amount of the Th1-related cytokine IFN-γ and a small amount of the Th17-related cytokine IL-17A are known to be secreted by LP CD4+ T cells." (PMID 31417110, 2019). "The results showed that TRAIL-treated CD4+ CD45RB(hi) T cells exhibited later-onset and less severe development of colitis." (PMID 31076664, 2019). "To further confirm that TRAIL-mediated suppression of colitogenic T cells in the development of colitis is via the TRAIL-R, we adoptively transferred TRAIL-treated splenic CD4+CD25− T cells from WT and TRAIL-R KO mice into Rag1 KO mice to induce colitis." (PMID 31076664, 2019). "We found that Asc−/−, but not Nlrp3−/− and Casp-1−/−, CD4+ T cells exacerbate T-cell induced colitis, suggesting that ASC in CD4+ T cells has a protective role." (PMID 31379813, 2019). "There also existed a drastic expansion of interferon γ (IFNγ)-producing CD4+ T helper cells (Th1) cells (CD4+IFNγ+Th1 cells) and NKp46+ IFNγ+ cells in the LP tissues of DSS-mediated colitis and E. coli O160:H7-colonized mice." (PMID 31707260, 2019). "This study confirmed that colitis is mediated by the Th1 response, in particular IFN-γ-producing CD4 T cells." (PMID 30949176, 2019). "The use of CD4+T cell-transfer colitis models revealed a new inhibitory mechanism of BBR, particularly in relation to colitis LP CD4+ T cells." (PMID 31417110, 2019). "Recently, it has been reported that a novel subset of helper CD4+ T cells producing IL-17A, namely, Th17 cells, was involved in the progression of DSS-induced colitis." (PMID 29888292, 2018). "FACS analysis further highlighted that Il-1r−/−Nlrp1aQ593P/Q593P mice have an increase in the total number of CD4+ T cells present in the cLP, during both SS and DSS-induced colitis." (PMID 30214011, 2018).
colitis (continued). "Hemizigosity in EP4 during T cell induced colitis in the adoptive T cell transfer colitis model is partially protective, and also affects IFNγ and IL2 production by MLN CD4+ cells." (PMID 30619314, 2018). "Rag1−/− mice received an adoptive transfer of CD4+CD25−CD45Bhi cells (Teff) from WT or mPGES-1−/− donor mice, and were monitored and evaluated for colitis progression for 10 subsequent weeks after transfer." (PMID 30619314, 2018). "Notably, while the Treg cell frequency within the CD4+ T cell population of Gimap5sph/sph mice is not affected, their progressive loss of suppressive function is thought to be a key factor in driving colitis in Gimap5sph/sph mice." (PMID 29382851, 2018). "Here we study the relationship between bacterial antigens and inflammatory stimuli, and miR-146a expression using IEC lines and models of colitis (trinitrobenzenesulfonic acid (TNBS), dextran sulfate sodium (DSS) and the CD4 + CD62L + T cell transfer model)." (PMID 30478292, 2018). "Taken together, we demonstrate that depending on the mode of colitis induction, IFNγ is critical for disease induction in the innate anti-CD40 mediated colitis model, whereas IFNγ production is dispensable in the CD4 T cell-dependent transfer colitis." (PMID 29416538, 2018). "Using a model of dextran sulfate sodium (DSS)-induced colitis, Qian and colleagues reported perturbation of numbers and frequency of NKG2D+CD4+ and NKG2D+CD8+ T cells in colon and spleen." (PMID 29910814, 2018). "In summary, we conclude that H. polygyrus infection prior to DSS-induced colitis further enhances the inflammatory response in the colon based on enhanced IL-6 and CXCL1 expression and increased CD4+ T cell activation." (PMID 28938014, 2017). "Some reports showed significant changes in CD4 and CD8 colonic T cell function in animal model of DSS-induced colitis." (PMID 28812128, 2017). "In this study, we provided evidence that in CD4+ T cells, SHP2 promotes the acute and persistent Th1-mediated immune response in colitis and CAC." (PMID 27935860, 2017). "Accumulated evidences have showed that the induction of CD4+ and CD8+ T cells apoptosis is beneficial to treat colitis." (PMID 28824631, 2017). "The infiltration of NK1.1− CD4+ NKG2D+ cells into the colon with colitis decreased, whereas the frequency of NK1.1− CD4+ NKG2D+ cells in the spleen of mice was enhanced." (PMID 28224733, 2017). "To confirm the Th1/17 responses in CS exposure-induced colitis, we analyzed the intracellular expression of IFN-γ and IL-17A on CD4+ T cells in MLNs and colonic LP." (PMID 29163466, 2017). "We investigated the expression profiles of miRNAs in a representative chronic murine colitis model for human IBD, the CD4+CD45RBhi T-cell transfer model." (PMID 29059189, 2017). "The frequencies of CD4+ CD25+ Foxp3+ and CD4+ CD25+ CD127− cells in the spleens from mice with DSS‐induced colitis were significantly down‐regulated by wogonin (100 mg/kg) treatment, compared with those in the solvent and DSS/solvent groups." (PMID 27641629, 2017). "In contrast to these data, on day 10 after colitis induction, a decreased production of IL-17A and IFN-γ by colonic CD4+ T cells was detected in rel−/− mice in comparison to WT animals." (PMID 28881761, 2017). "In T-cell adoptive transfer-induced colitis, the GLP-1 expression in colonic tissue was significantly diminished in SCID mice with adoptive transfer of CD4+ T cell when compared with control mice." (PMID 29270177, 2017). "CD4+ T cells are known to accumulate in the intestine during IBD, and during DSS colitis, T cells that are specific against oral antigens develop." (PMID 28938014, 2017). "Results show that the frequency of NK1.1− CD4+ NKG2D+ T cells in colon is negatively correlated with colitis induced by DSS, and NK1.1− CD4+ NKG2D+ T cell differs from NK1.1+ CD4+ NKG2D+ T cells in terms of cell membrane markers and transcriptional RNAs." (PMID 28224733, 2017).
colitis (continued). "In addition, because a CD62LlowCD44high phenotype has been reported for colitogenic CD4+ memory T cells in murine colitis models, aiTregs that are reprogrammed as Th2-type cells might be retained as a pathogenic memory T-cell subset in the MLNs or other tissues of EW-fed OVA23-3 and R23-3 mice." (PMID 28234975, 2017). "When NK1.1− CD4+ NKG2D+ cells were pre‐incubated with TGF‐β antibody in vitro, the protective effect against colitis by adoptive transfusion almost disappeared." (PMID 28224733, 2017). "We showed that contrary to Rag2-/- mice, in which adoptive transfer of naïve CD4+CD45RBHi T cells requires typically 6–8 weeks for the development of moderate disease, T cell-transferred DKO mice developed rapidly progressive colitis in less than two weeks." (PMID 27050757, 2016). "DSS-induced colitis is mediated by Th1 and Th17 responses, resulting in increased numbers of IFN-γ- and IL-17A-producing CD4 T cells in the inflamed colonic tissue." (PMID 27058552, 2016). "CCR5 gene ablation reduced the mucosal recruitment and activation of CCR5-bearing CD4+ and CD11b+ leukocytes, resulting in profound attenuation of signs and symptoms of inflammation in the TNBS and transfer models of colitis." (PMID 27492684, 2016). "In this paper, we found that DSS-induced colitis was exacerbated in IL21RKO mice with C57BL/6 background, in which CD4+ T cells in the LP of large intestine produced higher levels of IFN-γ but less Th2-type cytokines than those in C57BL/6 mice." (PMID 27545302, 2016). "In the original paper, the reconstitution of SCID mice with naive CD4+ T cells and OVA-specific CD4+IL-10+ T cell clones resulted in prevention of colitis." (PMID 27683580, 2016). "We also found KLRG1 expression significantly increased in both CD4+ and CD8+ T cells in colon cancer, colitis and ovarian cancer." (PMID 27557510, 2016). "Similar outcomes of CD4+CD25− Foxp3+ T cells and their functions were reported in animal models of experimental colitis." (PMID 26728323, 2016). "In this regard, the adoptive transfer of MDSCs fromgp130757F/F mice intoRag1−/− mice (which do not developfunctional T cells) with DSS- or CD4+CD25−T cell transfer-induced colitis could help to reveal the underlying contribution ofinnate and adaptive immune responses." (PMID 26848037, 2016). "At Day 8 of DSS-induced colitis, the percentage of CD4+ T cells expressing CD25+ (CD25+CD4+ T cells), which consisted of effector T cells and Tregs, in the colon of WT mice was similar to that of CCR7KO mice." (PMID 26908454, 2016). "Co-transfer of either CD4+CD45RBlo or Treg-of-B cells reduced the levels of IFN-γ, tumor necrosis factor (TNF)-α, IL-6, and IL-17 in the MLNs of mice with colitis." (PMID 27581189, 2016). "Compared to the control, Th1 cell populations (CD4+IFNγ+) and Th17 subsets (CD4+IL-17A+) increased in the spleen, MLN and colon tissues of mice with colitis as well as the enhanced concentrations of IFNγ and IL-17 in colon homogenate supernatants." (PMID 26728323, 2016). "To elucidate the impact of RORγt and T-bet expression on the colitogenic potential of T cells, we transferred Rag1−/− mice with CD4+ T cells from C57BL/6 WT, Tbx21−/− or Rorc−/− donors and assessed the development of colitis." (PMID 27193261, 2016). "In line with this, we found that Th17 (CD4+IL-17A+) and Th2 (CD4+IL-4+ and CD4+ IL-5+) obviously decreased in IL-21RKO mice with DSS-induced colitis." (PMID 27545302, 2016). "Our findings support a model whereby the interplay between B lymphocytes and a diversified naïve T cell repertoire is critical for the generation of CD4+CD25+Foxp3+ pTreg cells and colitis suppression." (PMID 27353032, 2016). "Nevertheless, this reduced tissue infiltrate was composed by augmented frequency of T helper (CD3+CD4+), T cytolytic (CD3+CD8+), and NKT cells (CD3+CD49b+) after exposure to the colitis trigger, DSS." (PMID 27403034, 2016).
colitis (continued). "During DSS-induced colitis, CCR7KO mice showed a higher percentage of Foxp3+CD4+ Tregs in every tissue sampled than the WT mice." (PMID 26908454, 2016). "Acute and chronic colitis were induced by administration of DSS or TNBS to wild-type and CCR5−/− mice or adoptive transfer of splenic naïve CD4+ T-cells from wild type or CCR5−/− mice into RAG-1−/−." (PMID 27492684, 2016). "Based on the immunosuppressive effect of G-MDSC exo on Th1 cells in DSS-induced murine colitis, we examined the role of G-MDSC exo in CD4+ T cell proliferation and IFN-γ secretion from CD4+ T cells in vitro." (PMID 26885611, 2016). "To determine the role of dietary plant sterols and stanols in prevention of intestinal inflammation, we tested for this in two models of experimental colitis, DSS and the CD4+CD45RBhi transfer colitis model (T cell transfer model)." (PMID 26501315, 2015). "In antigen-specific colitis models, the transfer of OVA-specific OT-II CD69−/− naïve CD4 T cells into RAG−/− animals followed by oral delivery of OVA protein resulted also in significant body weight loss and severe colitis." (PMID 25759842, 2015). "In a transfer model of colitis, it was shown that co-transfer of CD4+CD62L− cells into SCID mice prevented colitis induced by CD4+CD62L+ cells only when those cells were derived from conventionally raised mice." (PMID 25666708, 2015). "In contrast, increased CD4+FoxP3+ cell population as well as secretion of TGF-β, prostaglandin E2 (PGE2) and lipoxin A4 (LXA4) was observed in TNBS-colitis mice treated with CTX compared with untreated TNBS-colitis mice." (PMID 25853847, 2015). "Disease establishment took place at ~15 weeks old animals when the expansion of CD4+ T-cells expressing IL-17, TNF and IFN-γ reached a threshold together with stabilization of colitis severity and accumulation of B272 molecules." (PMID 26125554, 2015). "HLA-B27 associated disease progression in rats was accompanied by the expansion of pro-inflammatory CD4+ T-cells expressing IL-17, TNF and IFN-γ as early as 6 weeks of age, and clinical symptoms (colitis) appeared at approximate 10 weeks of age." (PMID 26125554, 2015). "Hence, the colitis in IL-2Rα−/− mice may be mediated by CD4+ CD45RBlow T cells." (PMID 25133396, 2014). "Our findings demonstrate that Trem1−/− mice not only show a highly attenuated CD4+ T cell- and DSS-induced colitis but also display significantly reduced lesion size and diminished morbidity during infections with L. major and influenza virus, respectively." (PMID 24453980, 2014). "Following the induction of colitis, the effect of n-3 PUFA on the resident CD4+ T cell effector subset populations (i.e., Th1, Th2, Th17, and Treg) was documented both locally (colon lamina propria and MLN) and systemically (spleen)." (PMID 25136149, 2014). "Based on this model, colitogenic CD4+ effector-memory T cells may be divided into two distinct populations, i.e., cytokine-producing effector cells and long-term surviving memory cells that are quiescent but retain the ability to induce colitis upon activation." (PMID 23840334, 2013). "FOXP3+ cells, CD4+CD25+FOXP3+ cells, and IL-10-secreting CD4+CD25+ T cells all play key roles in the regulation and suppression of DSS-induced colitis." (PMID 23864893, 2013). "To further assess the roles of CXCR6+ and CXCR6− T cells in the pathogenesis of colitis, we next performed adoptive retransfer of LP CXCR6+ and CXCR6− CD4+ T cells recovered from the inflamed colon." (PMID 23840334, 2013). "CD69 KO mice showed reduced colitis in both acute and chronic DSS-induced colitis models, and CD69 was highly expressed on the infiltrating CD4 T cells in DSS-treated WT mice." (PMID 23785429, 2013). "In vivo CD69−/− CD4 T cells accumulate in the intestine in higher numbers than B6 CD4 T cells as observed in competitive homing assay, dextran sodium sulphate (DSS)-induced colitis and antigen-specific transfer colitis." (PMID 23776480, 2013).
colitis (continued). "This subset has been subsequently characterized as the CD4+CD25+FOXP3+ fraction, and it has been shown how the transfer of these cells does not only prevent but also cures experimental colitis in mice." (PMID 24063002, 2013). "CD4+LAP+ Treg cells induced by mucosal antigens, such as anti-CD3 antibody, significantly suppressed colitis, multiple sclerosis, systemic lupus erythematosus, and diabetes." (PMID 24385687, 2013). "A number of studies have shown that CD4+LAP+ Treg cells suppress the Teff cell responses and protect mice from colitis, multiple sclerosis, systemic lupus erythematosus, and diabetes via the secretion of TGF-β and/or IL-10." (PMID 24385687, 2013). "Therefore, CXCR6 could well be a functional marker for the Th17-type effector, but that CXCR6 deficiency would not affect the development of colitis in a Th1-dominant model such as the CD4+CD45RBhigh cell-transferred model." (PMID 23840334, 2013). "In this model, Rag1−/− mice transferred with naive CD4+CD25−CD45RBhi T cells develop wasting disease and colitis with splenomegaly, mesenteric lymph node (MLN) enlargement, and severe leukocytic infiltration of the colon." (PMID 23200826, 2012). "Flow cytometry confirmed that the combination of colitis and HFD increased leukocyte migration and activation in the lamina propria, as seen for neutrophils, T helper (CD4+) cells, B (CD 19+) cells and activated macrophages (MOMA+ CD80+)." (PMID 22073943, 2011). "The CD4+FoxP3+CD103+ subset expresses CTLA-4; suppresses T cell proliferation in vitro; and protects mice from colitis in the severe combined immunodeficient (SCID) transfer model in vivo." (PMID 21966415, 2011). "However, although CD4+CD25+FoxP3+regulatory T cells (Tregs) are known to suppress Th1-mediated colitis, it is not clear whether they control Th2 –associated pathologies of the large intestine which characterise several helminth infections." (PMID 21858239, 2011). "In colon biopsy samples from IBD patients, CD4+ T cells show markedly increased pyruvate dehydrogenase kinase (PDK) expression, and PDK4 inhibition alleviates intestinal inflammation in a DSS-induced murine colitis model." (PMID 41476956, 2025). "Secondly, patients with immune-mediated enterocolitis exhibited significantly higher levels of CD4+ T cells and lower levels of Tregs compared to those without colitis, thereby markedly reducing the colitis-free interval." (PMID 40959085, 2025). "Notably, similar to CD4+ and CD8+ T cells, B cells also showed a significant increase in glucose uptake during acute colitis, which returned to baseline levels during remission." (PMID 41007657, 2025). "Moreover, while CD4+ and CD8+ T cells show increased glucose uptake in acute DSS colitis, they display impaired glucose consumption in its chronic phase, a condition that persists until the remission phase." (PMID 41007657, 2025). "Indeed, B. fragilis secretes the immunomodulatory molecule polysaccharide A (PSA) via outer membrane vesicles, which facilitates the conversion of naïve CD4+ T cells into FOXP3+ Tregs, ultimately protecting mice from experimental colitis." (PMID 40309194, 2025). "Activation of caspase-1, a key effector of the inflammasome complex, has been observed to contribute to CD4 T cell depletion during HIV infection, while blocking IL-18 signaling in T cells may exacerbate disease severity in murine colitis models." (PMID 40530419, 2025). "Here, we report that specifically CD4+ and CD8+ T cells in the colon produce significantly less mitochondrial reactive oxygen species and have smaller mitochondria during chronic DSS-induced colitis in mice, a phenotype which is resolved during remission." (PMID 41007657, 2025). "In addition, CD4+ and CD8+ T cells exhibit increased glucose uptake during acute but defective glucose consumption during chronic DSS colitis." (PMID 41007657, 2025). "In IBD mouse model, a lack of IFN-γ in CD4 T-cells prevents the development of Dextran Sulfate Sodium (DSS)-induced colitis." (PMID 40099014, 2025).